Y_RNA (Y RNA )
Gene: Miscellaneous RNA gene on chromosome 7 (73,067,231 to 73,067,332, forward strand). Ensembl gene ENSG00000274984.
Homologues: Orthologues: chimpanzee Y_RNA (99% identical), pig Y_RNA (75% identical). Paralogues in human: Y_RNA (100% identical), Y_RNA (97% identical), Y_RNA (93% identical), Y_RNA (92% identical), Y_RNA (90% identical), Y_RNA (89% identical), Y_RNA (87% identical), Y_RNA (85% identical), RNY3 (84% identical), RNY3P12 (84% identical), Y_RNA (84% identical), RNY3P1 (83% identical), and 98 more.